APOE (apolipoprotein E)
Diseases named in the same sentence as APOE in open-access papers (continued):
Sharing a sentence is not in itself a finding about the gene and the disease.
atherosclerosis (continued). "Treatment of apolipoprotein E-deficient (ApoE−/−) mice with FGF-21 reduced atherosclerosis formation by increasing adiponectin expression and inhibiting ER stress, NLRP3 inflammasome activation, and factor-associated suicide (FAS) signaling." (PMID 35177953, 2022). "This regulation is affected by APOE polymorphism, and APOE ɛ4 polymorphism is known to increase the risk of atherosclerosis and neurodegenerative disorders, including Alzheimer’s disease and dementia." (PMID 36005151, 2022). "On the one hand, experimental atherosclerosis studies show that treatment with recombinant IL-6 (rIL-6) promotes early atherosclerosis in C57Bl/6 and ApoE-deficient mice." (PMID 35402550, 2022). "We tested the association of APOE locus lead SNVs with clinical, metabolic, and biochemical phenotypes; hematological parameters; lifestyle habits; and risk factors for atherosclerosis." (PMID 36011277, 2022). "Selective MPO inhibitors or polymorphisms of the MPO gene are leading to decreased MPO activity, and reduced the risk or progression of atherosclerosis in apoE−/− mice and humans, respectively." (PMID 36297390, 2022). "Using two types of BMP4-DKO mouse models, our previous study found that deficiency of BMP4 in PVAT aggravated atherosclerosis development in ApoE–/– mice." (PMID 36457800, 2022). "A global deficiency of PGRN increases atherosclerosis in ApoE−/− mice, although the mechanisms responsible for this phenotype are unclear." (PMID 35453521, 2022). "Xiong and coworkers reported the anti-inflammatory role of Vs-II (N-terminal fragment of CgA containing Vs-I; CgA1-113) in an apolipoprotein E-deficient (ApoE−/−) mice model fed with a high-fat diet developing atherosclerosis." (PMID 36297449, 2022). "Differences have previously been found in the susceptibility of male and female APOE KO mice to atherosclerosis, with a higher predisposition in females." (PMID 36139044, 2022). "HIV-associated atherosclerosis has also been investigated in a novel mouse model, Tg26+/−/ApoE−/− mice." (PMID 33459922, 2022). "The comparison of young vs. older apoE-deficient mice sheds light on lipidomic changes during the progression of atherosclerosis." (PMID 34928417, 2022). "Bone marrow transplantation from Glut1-deficient mice into irradiated ApoE−/− mice showed that Glut1 deficiency inhibited myelopoiesis, decreased glucose uptake in the plaque, and slowed atherosclerosis progression." (PMID 35348183, 2022). "We also chose to carry out the TBI experimental model on apolipoprotein E-deficient (ApoE−/−) mice with atherosclerosis to observe the long-term effects of TBI on this pathology." (PMID 35456980, 2022). "In vivo, the direct relationship between PCSK9 and atherosclerosis was investigated by utilizing Apolipoprotein E (ApoE) deficient mice." (PMID 36005422, 2022). "ApoE deficiency in ApoE−/− mice leads to robust atherosclerosis with exacerbated vascular inflammation in addition to the elevated plasma lipid levels caused by impaired lipoprotein clearance." (PMID 36077289, 2022). "Among the four flavanones tested for their anti-atherosclerosis potential in apolipoprotein E-deficient (ApoE−/−) mice, naringin showed the most potent anti-atherogenic effect, followed by hesperidin, naringenin, and hesperetin." (PMID 35204122, 2022). "In this study, we attempted to investigate the potential effect of a HO-1 inducer, hemin, and a HO-1 inhibitor, Tin-protoporphyrin IX (SnPP), on the progression of atherosclerosis in ApoE deficient mice." (PMID 35281895, 2022).
atherosclerosis (continued). "A direct causal relationship between HHCY induction and accelerated atherosclerosis has been reported in apolipoprotein E (apoE)-deficient mice." (PMID 36611302, 2022). "ApoE3-Leiden animals show a less pronounced tendency to develop atherosclerosis than ApoE−/− variants but have other advantages that come into play." (PMID 35760040, 2022). "ApoE-deficient mouse is a commonly used animal model for atherosclerosis, which is predisposed by obesity and inflammation." (PMID 35958261, 2022). "Animals with ApoE knockout (KO) have been used to study atherosclerosis and hyperlipidemia while an increasing number of researchers have recently focused on the association of ApoE with hearing loss." (PMID 36139057, 2022). "The effect of DP on lipid metabolism in ApoE−/− mice was investigated since dyslipidemia is an important risk factor for atherosclerosis." (PMID 35215505, 2022). "Our results showed that global SRC-3 deficiency on the ApoE-/- background ameliorated the development of atherosclerosis." (PMID 36263184, 2022). "Our study revealed that intraperitoneal (i.p.)injection of DHC in apolipoprotein E-deficient (ApoE−/−) mice not only inhibited atherosclerosis development but also improved aortic compliance and increased plaque stability." (PMID 34552216, 2022). "ApoE knockout mice were found to present high plasma cholesterol levels, which have been associated with the development of atherosclerosis and brain–blood barrier breakdown." (PMID 35937834, 2022). "Luseogliflozin regulates the expression of multiple mRNA, including MMP9, and inhibits the progression of atherosclerosis in diabetic APOE-deficient mice." (PMID 35677689, 2022). "IL-17A blockade in apoE-deficient mice shows a reduction in atherosclerosis development and decreases the vulnerability of plaque, which suggests a similar pathway of ACS and uveitis in patients with AS." (PMID 35757729, 2022). "Exemplarily, ApoE−/−mice repopulated with CXCR4-deficient bone marrow displayed reduced lesions in injury-driven atherosclerosis but exacerbated lesion formation in lipid-driven atherosclerosis." (PMID 35055054, 2022). "Several FTO polymorphisms are associated with increased risk for weight gain and the APOE ε4 variant is a genetic risk factor for atherosclerosis and CVD in humans." (PMID 35454109, 2022). "An apolipoprotein E-deficient (ApoE−/−) mouse model is a pre-clinical model that is widely used to study the pathophysiology of vascular plaque formation and atherosclerosis." (PMID 35625895, 2022). "Atherosclerosis, dyslipidemia, and hypertension have a complex interaction, and the causations with APOE need further investigation." (PMID 35154509, 2022). "In the present study, we demonstrated that ApoE deficiency induces iron-overload as well as atherosclerosis in the aortic tissues." (PMID 35669479, 2022). "Transgenic mice, such as apolipoprotein-E (ApoE) knockout mice, have been used to elaborate on the mechanisms underlying the development of atherosclerosis." (PMID 34571110, 2022). "ApoE deficiency has been shown to alter the plasma cholesterol concentration in lipoproteins in atherosclerosis and CKD." (PMID 35629966, 2022). "We also reported that Spirulysat® supplementation prevent metabolic syndrome-associated metabolic disturbances in hamsters and atherosclerosis development in apolipoprotein E-deficient mice." (PMID 35877734, 2022). "It has been suggested that THBS1 plays a role in the pathogenesis of atherosclerosis, where its absence was shown to accelerate atherosclerosis in apolipoprotein E deficient mice." (PMID 35109843, 2022). "An in vivo study focused on evaluating the effect of ANs on apolipoprotein E-deficient (apoE−/−) mice to investigate the early stage of atherosclerosis." (PMID 35807504, 2022).
atherosclerosis (continued). "In order to assess the role of SMC-specific NF-κB signalling in atherosclerosis, NEMOSMCiKO mice were backcrossed into the ApoE-deficient genetic background." (PMID 35869246, 2022). "Nakashima also nicely described the development of atherosclerosis in mice with apoE deficiency and fed a Western diet." (PMID 35795646, 2022). "APOE has been implicated in Alzheimer’s disease, atherosclerosis, and other unresolvable inflammatory conditions but a common mechanism of action remains elusive." (PMID 35379280, 2022). "Elevated serum IL-12 levels have been observed in ApoE-deficient mice, and they are associated with the progression of atherosclerosis." (PMID 36012327, 2022). "ApoE has been identified as a major risk factor for cardiovascular disease and is correlated with an increased risk of atherosclerosis." (PMID 36360235, 2022). "Our previous study also showed that loss of Sema4d in apolipoprotein-E (ApoE)-deficient mice retards the progression of atherosclerosis." (PMID 35045890, 2022). "In the present study, we have shown that DHC attenuates atherosclerosis and reduces systemic and vascular inflammation in apolipoprotein E-deficient (ApoE−/−) mice." (PMID 34552216, 2022). "Increased HDAC9 mRNA levels have been identified in human carotid atherosclerotic plaques, and knockout of HDAC9 in a mouse model for atherosclerosis, the apolipoprotein E-deficient (ApoE-/-) mouse, was associated with reduced aortic atherosclerosis." (PMID 35433850, 2022). "One of the two utilized heterozygous MALAT1-deficient ApoE−/− mice to access the influence of the lncRNA on atherosclerosis." (PMID 35548442, 2022). "To functionally investigate the role of miR-223-3p in vulnerable atherosclerotic lesions, we applied the well-established mice atherosclerosis HFDs, in which atherosclerotic lesions were induced in apolipoprotein-E deficient (ApoE-/-) mice by a high-fat diet." (PMID 35202001, 2022). "Atherosclerosis was reported to be induced in apolipoprotein E (ApoE)-deficient mice, but arteriosclerosis and fat accumulation in macrophages were suppressed in ApoE and PPM1D double knockout mice." (PMID 36233344, 2022). "Pak1 expression and activity are increased in atherosclerosis-prone apolipoprotein E-deficient (ApoE-/-) mice." (PMID 39899001, 2022). "The causative role of ROS-mediated damage in atherosclerosis development has been demonstrated in studies using apolipoprotein E knock-out (apoE–/–) mice." (PMID 34026846, 2021). "Here, we investigated a causative action of P. gingivalis in inducing atherosclerosis using ApoE knock-out mice under Western diet as a pathophysiological model." (PMID 33976982, 2021). "Using the animal model of atherosclerosis-prone apolipoprotein E-deficient (ApoE−/−) mice fed a western high-fat diet, several groups demonstrated that miR-34a levels increase in the aortas and serum at early and late stages of atherosclerosis." (PMID 34698884, 2021). "ApoE genetic variations are associated not only with plasma lipid levels but also with atherosclerosis risk and pathobiology of neurodegenerative diseases." (PMID 34441867, 2021). "A study assessed the effects of long-term use of Empagliflozin on the indicators and parameters associated with atherosclerosis and the development thereof in apolipoprotein E gene knockout [Apo-E (-/-)] mice aortas." (PMID 34341711, 2021). "In this regard, silencing IL-1β in apoE-deficient mice (ApoE−/−) that are susceptible to atherosclerosis has revealed a reduction in the rate and extent of coronary atherosclerosis." (PMID 32378144, 2021). "Here, we used apolipoprotein E deficient (apoE–/–) mice, a model of atherosclerosis, to investigate the impact of this hypomethylating KD on the systemic levels of BHB plasma levels, inflammation, and methylating index AdoMet/AdoHcy." (PMID 34684577, 2021).
atherosclerosis (continued). "Mice deficient for Aire were crossbred to apolipoprotein E-deficient mice to obtain atherosclerosis-prone Aire−/−Apoe−/− mice, which were fed a regular chow diet (CD) or western-type diet (WD)." (PMID 35097028, 2021). "Its function in atherosclerosis has been investigated in apolipoprotein E-deficient (ApoE−/−) mice with mixed results." (PMID 33883651, 2021). "For instance, platelets CXCL4 and CCL5 have been shown to form stable heterodimers whose disruption prevents atherosclerosis in ApoE-deficient atherosclerotic mice." (PMID 34360659, 2021). "Consistently, the deficiency of ApoE in mice develops hypercholesterolemia, inflammation, and atherosclerosis, whereas apoE expression protects the mice against this phenotype." (PMID 34441867, 2021). "As the accumulation of lipid-laden macrophage foam cells in the intima of inflamed arteries is a hallmark of atherosclerosis, the prevalence of macrophages within the atherosclerotic plaque was evaluated in ApoE−/− mice after treatment." (PMID 34564147, 2021). "Then, ApoE-deficient (ApoE−/−) mouse fed a high-fat diet, a widely used animal model for atherosclerosis-related research, was recruited to evaluate the in vivo anti-atherosclerotic efficacy of GM3-rHDL nanoparticles." (PMID 34948420, 2021). "In this study, they also showed that combined apoE and TREML4-deficient mice developed less atherosclerosis with reduced macrophage and monocyte content as well as decreased collagen deposition, compared with apoE-deficient control mice." (PMID 34572399, 2021). "Atherosclerosis progression was slower in the three groups that were injected with various ApoE variants than in the other two groups." (PMID 33663537, 2021). "For instance, both hemizygous Klf2 germline deletion or endothelial-specific Klf4 loss sensitized atheroprone apolipoprotein E–deficient (ApoE−/−) mice to high fat diet-induced atherosclerosis." (PMID 34299213, 2021). "The results show that with the disease progression, APOE ε4 carriers had alterations in metabolites associated with increased Aβ retention, reducing atherosclerosis, and the impaired TCA cycle and oxidative phosphorylation." (PMID 35265943, 2021). "Here, we proved the effect of GDF-15 of autophagy by using, in vitro, a human atherosclerosis MΦ model and in vivo GDF-15-deficient (GDF-15−/−) mice within an experimental atherosclerosis apolipoprotein (apo)E knockout (ApoE−/−) mouse model." (PMID 34571994, 2021). "We previously reported that ERK1/2 inhibition synergizes liver X receptor (LXR)-reduced atherosclerosis in apoE deficient (apoE-/-) mice by enhancing reverse cholesterol transport and ATP-binding cassette transporter A1 (ABCA1) expression." (PMID 33391525, 2021). "As found in earlier studies, atherosclerosis in ApoE mice was associated with a decrease in the expression of GPx4 as well as changes in other markers of ferroptosis." (PMID 34579115, 2021). "Therapeutic effects on atherosclerosis and the systemic leaky expression effects in vivo of the functionalized exosomes were analyzed in ApoE-/- (Apolipoprotein E-deficient) mice." (PMID 34815799, 2021). "The Cyp17A1 heterozygous mice were backcrossed to the commonly used atherogenic ApoE (Apolipoprotein E) deficient genetic background to induce atherosclerosis and obesity when feeding a Western-type diet (WTD)." (PMID 34070975, 2021). "Another study showed a similar result that specific deletion of macrophage LRP1 in the ApoE deficient mice increased atherosclerosis, which is concomitant with the accumulation of apoptotic cells and proinflammatory monocytes in lesions." (PMID 34124208, 2021). "Atherosclerosis was ameliorated upon deletion of the Casp1 gene in apolipoprotein E deficiency (ApoE−/−) mice (also a widely used atherosclerosis mouse model)." (PMID 33535473, 2021).
atherosclerosis (continued). "In CXCL10-knocked out/apolipoprotein E-deficient mice, the atherosclerosis progression was shown to be well-correlated with enhanced Treg cell numbers and their subsequent effect on the reduction of atherosclerotic lesion formations." (PMID 34835155, 2021). "Atherosclerosis development was analyzed in apolipoprotein E-deficient (ApoE−/−) mice fed a high-fat diet (HFD) using Oil Red O staining and H&E staining." (PMID 34638650, 2021). "Chronic infusion of catestatin, vasostatin-1, or vasostatin-2 suppresses the development of atherosclerosis of the aorta in apolipoprotein E-deficient mice." (PMID 34204153, 2021). "In ApoE-deficient mice dapagliflozin inhibited interleukin-1β secretion by macrophages and reduced atherosclerosis via the ROS-NLRP3-caspase-1 pathway." (PMID 34131781, 2021). "Loss of biglycan led to enhanced thrombin generation and platelet activation in ApoE-deficient mice, suggesting a role for biglycan in inflammation and atherosclerosis." (PMID 34830059, 2021). "ApoE−/− mouse model, high-fat diet mouse, and rabbit model constitute the primary in vivo platforms for studying underlying pharmaceutical mechanisms in atherosclerosis." (PMID 34054550, 2021). "In Apolipoprotein E-deficient (ApoE−/−) mice, an established mouse model of atherosclerosis, GLO1 inhibition by bromobenzyl-glutathione cyclopentyl diester increased vascular adhesion and augment atherogenesis." (PMID 34440621, 2021). "It was shown that the inactivation of macrophage ABCA1 promotes increased atherosclerosis in ApoE-deficient mice." (PMID 34759279, 2021). "Our study focused on the commonly used healthy Bl6 mice and the apolipoprotein E-deficient mice, a model for atherosclerosis, which have a Bl6 background." (PMID 33810147, 2021). "Apolipoprotein-E deficient (apoE−/−) mice are a common model to study the progression of atherosclerosis." (PMID 33557105, 2021). "One study, however, found no atheroprotective effects concomitant to the reduction of GSLs in atherosclerosis-prone ApoE-deficient mice." (PMID 33855029, 2021). "Lately, SP-8365—a new inhibitor of the complex CyPA/EMMPRIN—was found effective for the treatment of atherosclerosis by reducing plaque progression and stabilizing vulnerable plaque in apoE-deficient mice." (PMID 33809359, 2021). "It has also been reported that the disruption of NRF2 expression attenuates the development of atherosclerosis in apolipoprotein E-deficient mice." (PMID 33451022, 2021). "This study compared the anti-atherosclerotic activity of SeNPs stabilized with chitosan (CS-SeNPs) and Na2SeO3 and the related mechanism in a high-fat-diet-fed apolipoprotein E-deficient mouse model of atherosclerosis." (PMID 34769040, 2021). "ApoE deficient mice will develop atherosclerosis on a normal chow diet, although a high fat or Western diet is often used to accelerate disease progression." (PMID 34579115, 2021). "Nox4 appears upregulated in ApoE null mice (ApoE−/−) and elevated levels of this enzyme in human arteries have been linked to the severity of atherosclerosis." (PMID 34573095, 2021). "One of the most prominent genes associated with atherosclerosis is apolipoprotein E (Apoe) and its corresponding protein is considered to be vital for the removal of lipoproteins that contain high amounts of cholesterol." (PMID 33800271, 2021). "Future tests on atherosclerosis-prone apolipoprotein E-deficient (Apoe−/−) mice are planned to assess the in vivo efficiency of the newly developed PET radiotracers and to investigate their in vivo characteristics." (PMID 34371717, 2021). "We have also revealed that the atherosclerosis-prone apolipoprotein E–deficient mice display a significant elevation of the IgM responses to the acrolein-specific epitopes (Lim, S.-Y., Itakura, M., and Uchida, K., unpublished observation)." (PMID 33839149, 2021).